SYP (synaptophysin)
Diseases named in the same sentence as SYP in open-access papers (continued):
Sharing a sentence is not in itself a finding about the gene and the disease.
schizophrenia (continued). "Reduced density of these boutons could contribute to the reduced density of layer III putative axon boutons in schizophrenia, revealed by the assessment of SYP-IR." (PMID 29375326, 2017). "Similarly, synaptophysin proteins were reduced by almost 30% in the CA1 region of schizophrenia subjects compared to controls." (PMID 27430010, 2016). "Therefore, reduced synaptophysin may contribute to dendritic spine reductions in auditory cortex in schizophrenia." (PMID 29375326, 2017). "Another study explored differences in synaptophysin, vesicular glutamate transporter 1 (vGLUT1), calcineurin, and Mitofusin-2 expression as a marker of synaptic activity in the ACC in schizophrenia and TRS." (PMID 40943517, 2025). "Here, we report the increased expression of SYP and another gene related to synaptic function (SV2C) in female schizophrenia patients." (PMID 39068467, 2024). "Downregulation of SYP gene and decreased synaptophysin and GAD1 expression in HC and PFC due to the administration of MAM in rats and as well as in schizophrenia patients." (PMID 36692676, 2023). "Previous studies have shown that SYP and PSD95 expression are decreased in some cortical areas in schizophrenia." (PMID 35781563, 2022). "The hypothesis of NMDA receptor hypofunction in schizophrenia is supported by findings of morphological changes in glutamatergic neuron dendrites of the cerebral cortex in patients with schizophrenia and of decreased levels of synaptophysin, which is an axon bouton marker." (PMID 32751985, 2020). "Finally, published results indicate that synaptophysin itself may be reduced in schizophrenia." (PMID 29375326, 2017). "However, quantitative examination of immunoreactive puncta within the auditory cortex demonstrated that the number of puncta for synaptophysin or vesicular glutamate transporters VGLUT1 and VGLUT2 was minimally altered or remained unchanged in schizophrenia." (PMID 40829937, 2025). "For example, synaptophysin (SYP), an essential molecule for neurotransmission, has been reported to be reduced in patients with schizophrenia; however, a contradicting report did not include tissue pH as a confounder." (PMID 37520228, 2023). "Of the two mRNA studies of synaptophysin in the hippocampus, one showed significantly decreased synaptophysin mRNA levels in schizophrenia, the other a non-significant reduction." (PMID 29511299, 2019). "The lack of differences between normal and schizophrenia cases in synaptophysin was observed previously in our quantitative immunohistochemical study of dysbindin-1 in the HF." (PMID 21390302, 2011). "This includes lower levels of synaptophysin and other synaptic vesicle proteins, lower transcript levels of SV2A, lower cortical dendritic spine density and other post-synaptic elements, and lower spine plasticity, in the context of unaltered neuronal numbers in schizophrenia." (PMID 37041418, 2023). "Using Western blotting on pSTG (n = 15) and HF (n = 15) synaptosomal fractions from schizophrenia cases and their matched controls, we discovered that synaptic dysbindin-1 is reduced in an isoform-specific manner in schizophrenia without changes in levels of synaptophysin or PSD-95." (PMID 21390302, 2011).
pheochromocytoma (19 papers, 2011 to 2026). "Standard neuroendocrine markers include chromogranin A and synaptophysin, which are typically positive in pheochromocytomas, confirming neuroendocrine differentiation." (PMID 40709162, 2025). "An immunohistochemical study indicated that this tumor was pheochromocytoma because of the neuroendocrine markers, such as vimentin, synaptophysin, S100, pan CK, and CD-56." (PMID 39290924, 2024). "The expression of chromogranin A and synaptophysin were consistent with the diagnosis of pheochromocytoma." (PMID 39822445, 2024). "In all cases the diagnosis of pheochromocytoma was histopathologically confirmed by immunohistochemistry - typical positive staining: synaptophysin and chromogranin and the presence of S100+ sustentacular cells in neoplasm." (PMID 35992110, 2022). "Pathology was consistent with bilateral pheochromocytoma with tumour cells reactive with chromogranin, synaptophysin and S100; proliferative index was low (Ki-67<1%)." (PMID 33815275, 2021). "Pathology was consistent with pheochromocytoma with tumour cells reactive with chromogranin, synaptophysin and S100; there was also presence of granular cytoplasmatic immunoreactivity for SDHB; proliferative index was low and PASS Score was 0/20." (PMID 33815275, 2021). "Pheochromocytomas usually have cell nests with abundant basophilic to amphophilic cytoplasm and are positive for synaptophysin and chromogranin." (PMID 25685588, 2015). "With regard to the differential diagnosis of pigmented pheochromocytoma, immunohistochemical studies are necessary, essentially with the neuroendocrine markers chromogranin and synaptophysin, and electron microscopy is also required." (PMID 21722390, 2011). "Histological and immunohistochemical analysis revealed the tumor’s characteristic organoid pattern (Zellballen) with chromogranin and synaptophysin positivity in principal cells and S100 protein staining in sustentacular cells, consistent with pheochromocytoma." (PMID 40162137, 2025). "Pigmented pheochromocytoma shows immunoreactivity for chromogranin, synaptophysin and enolase." (PMID 21722390, 2011). "Pheochromocytomas and abdominal paragangliomas stain positive for neuroendocrine markers CgA, SYP, ISL1, INSM1 and, often, GATA3; subsets of cases may display an intricate network of supporting sustentacular cells which are highlighted by an S100 or SOX10 stain." (PMID 37685605, 2023). "Both the pheochromocytoma component and ganglioneuroma component of the tumor were stained positively for neuron-specific enolase (NSE), synaptophysin (Syn) and Vimintin(Vim)." (PMID 23587063, 2013). "Immunohistochemistry revealed synaptophysin positivity with negative chromogranin A staining, supporting a diagnosis of pheochromocytoma." (PMID 42095012, 2026). "Although the tumor was unexpectedly negative for immunolabeling to tyrosine hydroxylase and synaptophysin, 25 and 15% of pheochromocytoma cases, respectively, can stain negative for these immunohistochemical markers." (PMID 41321567, 2025). "For instance, pheochromocytomas are specific for chromogranin A and CD56, while an adrenocortical origin would be suggested by positive for calretinin, MART-1, and inhibin A. Synaptophysin levels can be elevated in both pheochromocytomas and adrenal cortical tumors." (PMID 39290924, 2024). "Among pheochromocytomas analyzed, 100% were positive for synaptophysin and chromogranin and all of them were negative for calretinin." (PMID 26989553, 2016). "The histological results show sustentacular cells of pheochromocytomas exhibiting immunoreactivity to the S-100 protein, which closely resembles the chief cells of typical adrenal medulla, displaying an immune response to CD56, chromogranin A, and synaptophysin." (PMID 39822445, 2024).
pheochromocytoma (continued). "Immunoreactivity to classic neuroendocrine markers such as CgA and synaptophysin is almost always present, and second-generation neuroendocrine markers ISL LIM Homeobox 1 (ISL1) and INSM1 have also been found as reliable markers of an adrenal medullary origin in pheochromocytoma." (PMID 35205664, 2022). "The absence of SF-1, chromogranin A/synaptophysin, AE1/AE3 cytokeratin, S-100, CD34, and HMB-45 ruled out pheochromocytoma, metastatic carcinoma, malignant peripheral nerve sheath tumor, angiosarcoma, and malignant melanoma, respectively." (PMID 38110958, 2023). "In addition, the lack of synaptophysin, AE1/AE3 cytokeratin, S-100 and CD34 expression ruled out pheochromocytoma, metastatic carcinoma, malignant peripheral nerve sheath tumor, and angiosarcoma, respectively." (PMID 38110958, 2023).
squamous cell carcinoma (18 papers, 2011 to 2026). A carcinoma arising from squamous epithelial cells. "The specificity of Musashi-1 for lung NEC tested with adenocarcinoma and squamous cell carcinoma (81%) was comparable to those of synaptophysin (82%) and CD56 (81%) and lower than those of chromogranin (96%) and INSM1 (87%)." (PMID 38067335, 2023). "Nevertheless, we utilized synaptophysin to validate neuroendocrine characteristics and to rule out the possibility of small cell variants of squamous cell carcinoma, lymphoma, and other blue round cell tumors." (PMID 39070322, 2024). "Nevertheless, the results of our present study confirmed the fact that poorly differentiated/basaloid squamous cell carcinomas must be differentiated from esophageal small-cell carcinomas by means of neuroendocrine markers (synaptophysin/chromogranin A) and a squamous-basal marker (e.g., p40)." (PMID 32556556, 2021). "The PDTOs were positive for subtype-specific markers; i.e., TTF-1 and CK-7 for adenocarcinomas, p63 and CK5/6 for squamous cell carcinomas, and CD56 and synaptophysin for small-cell lung cancer." (PMID 40723176, 2025). "In their case, immunohistochemical analyses including synaptophysin, chromogranin, neuron-specific enolase (NSE), and Leu-7 were performed to identify neuroendocrine cells, and squamous cell carcinoma components were weakly positive for NSE." (PMID 26943678, 2016). "In our case, after revealing squamous cell carcinoma by HMWCK and p63, additional staining analyses with synaptophysin and chromogranin were performed to exclude a neuroendocrine component." (PMID 26943678, 2016). "Cytomorphology and expression of CK5 and p63 favoured squamous cell carcinoma diagnosis, while expression of neuroendocine markers (CD56, chromogranin and synaptophysin) and appropriate morphology established the diagnosis of large cell neuroendocrine carcinoma." (PMID 21949883, 2011). "Expression of neuroendocrine markers such as synaptophysin, INSM1, and CD56 confirmed neuroendocrine differentiation, while negative p40 ruled out poorly differentiated squamous cell carcinoma." (PMID 40909459, 2025).
Anxiety (17 papers, 2015 to 2025). Intense feelings of nervousness, tension, or panic often arise in response to interpersonal stresses. "Rats with neonatal hypoxia-ischemia or maternally separation (MS180min) cause increased levels of anxiety and decreased levels of synaptophysin in the hippocampus." (PMID 29132299, 2017). "Treadmill exercise appears to improve spatial learning ability and alleviate anxiety-like behaviors in sedentary mice, possibly through modulating ROS-synaptophysin pathways." (PMID 39469236, 2024). "Physical exercise improves anxiety-like behavior and restores down-regulation of synaptophysin in the hippocampus of 3xTg-AD mice." (PMID 29132299, 2017). "For example, mice with traumatic brain injury show increased anxiety-like behavior and decreased levels of synaptophysin in the hippocampus." (PMID 29132299, 2017). "Chronic central administration of ghrelin produces an increase in anxiety-like behavior and synaptophysin gene expression in the amygdala in rats." (PMID 29132299, 2017). "In a model of complex regional pain syndrome, fracture/cast mice show signs of anxiety and reduction of synaptophysin levels in the hippocampus." (PMID 29132299, 2017). "Recent studies have suggested that synaptophysin is involved in anxiety behavior and cognitive process." (PMID 29132299, 2017). "Predator threat stress promotes long lasting anxiety-like behavior and up-regulates synaptophysin gene expression in the amygdala in rats." (PMID 29132299, 2017). "Here we confirmed that increased expression of PSD-95 and synaptophysin was related to improved long-term memory and decreased anxiety due to enhanced synaptic plasticity." (PMID 27900211, 2016). "Moreover, in the rats with anxiety-like phenotype, synaptophysin, a marker for synaptic density found in the hippocampus, was increased, which is supported by previous reports." (PMID 30740068, 2018). "Recent researches have suggested that synaptophysin is involved in anxiety behavior." (PMID 29132299, 2017). "Finally, we assessed whether there are apoE isoform- or test history (i.e., contextual fear or passive avoidance memory extinction)-dependent effects on measures of anxiety and/or depressive-like behavior or on hippocampal levels of synaptophysin, MAP-2, or tau." (PMID 40565282, 2025). "Levels of synaptophysin, a synaptic vesicle-associated protein involved in the formation of synapses in cultured hippocampal neurons, correlate with cognitive performance and are altered in aged mice as well; they also correlate with measures of anxiety and cognition in aged non-human primates." (PMID 40565282, 2025). "Herein, we established a maternal separation (MS) and chronic restraint stress (CRS) model and evaluated anxiety-like behavior and cognitive function (e.g., learning and memory) in adulthood through behavioral examination and analyzed hippocampal expression levels of PSD95 and synaptophysin." (PMID 33381149, 2020).
breast carcinoma (17 papers, 2011 to 2025). "INSM1 expression has also been associated with improved disease-free survival in luminal breast cancers, supporting its inclusion alongside synaptophysin ± chromogranin in diagnostic panels." (PMID 40909459, 2025). "In a preliminary investigation we observed that synaptophysin or chromogranin were highly expressed in MMTV associated mouse mammary tumours." (PMID 28523075, 2017). "Recently, a tissue microarray analysis showed that adding chromogranin to synaptophysin detects an extra 4.2% of breast cancer cases with neuroendocrine differentiation, while INSM1 identifies 15% of cases negative for both." (PMID 40909459, 2025). "These neoplasms have a similar clinical presentation as conventional breast carcinomas, differing mainly in their histopathology and expression of neuroendocrine (NE) markers, chromogranin and synaptophysin." (PMID 37113730, 2023). "It is defined as uncommon subtype of breast cancer in which more than 50% of the tumor cells express at least one neuroendocrine marker (synaptophysin, chromogranin A, or neuron-specific enolase)." (PMID 33692758, 2021). "Initially, the World Health Organisation(WHO) classified breast cancers with neuroendocrine features as those breast tumours with over 50% of positive synaptophysin or chromogranin cancer cells." (PMID 28523075, 2017). "This has since been modified to include breast cancers with any number of synaptophysin or chromogranin positive cancer cells." (PMID 28523075, 2017). "The different positivity for synaptophysin and chromogranin between the human breast cancer and mouse mammary tumour was p = 0.001 and 0.001 respectively, that is highly significant." (PMID 28523075, 2017). "Towards the end of the 1980s chromogranin and synaptophysin were found to be neuroendocrine differentiation markers and tumors that were once denominated ‘argylophilic breast carcinoma’ also tested positive for these markers." (PMID 23734899, 2013). "As detailed in the Introduction, immunostaining with ENO2, chromogranin A and synaptophysin have been used extensively to determine neuroendocrine differentiation in breast cancer." (PMID 22098917, 2011). "One human breast cancer specimen was positive for both Synaptophysin and Chromogranin." (PMID 28523075, 2017). "As synaptophysin and chromogranin proteins are expressed in human breast cancers which have similar histological characteristics to MMTV positive mouse mammary tumours, we hypothesised that MMTV may be the underlying causal factor." (PMID 28523075, 2017). "Indeed, when in some studies neuroendocrine markers have been screened from unselected breast carcinomas, up to 10.4% of all breast cancers showed some synaptophysin or chromogranin A expression." (PMID 28118820, 2017). "However, despite the small numbers of mouse mammary tumours in this study, the universal expression in these specimens of synaptophysin and chromogranin proteins is striking." (PMID 28523075, 2017). "However, despite the small numbers of MMTV positive mouse mammary tumours in this study, the universal expression in these specimens of synaptophysin and chromogranin proteins is striking." (PMID 28523075, 2017). "Among others, synaptophysin (SYP), a conventional neuroendocrine marker, is upregulated in prostate adenocarcinoma (PRAD) and breast cancer (BRCA)." (PMID 38926911, 2024). "This pattern of synaptophysin and chromogranin expression is very different from their expression in MMTV positive human breast cancers." (PMID 28523075, 2017). "The expression of synaptophysin and chromogranin proteins in MMTV positive human breast cancers was much less prevalent than in MMTV positive mouse mammary tumours." (PMID 28523075, 2017). "This pattern of synaptophysin and chromogranin expression is very different from the MMTV human breast cancers." (PMID 28523075, 2017). "The expression of synaptophysin and chromogranin in MMTV positive human breast cancers was much less prevalent (3 of 22 – 14%)." (PMID 28523075, 2017).